MT-TR (mitochondrially encoded tRNA-Arg (CGN))
Synonyms: trnR; formerly MTTR
Gene: Mitochondrial transfer RNA gene on chromosome MT (10,405 to 10,469, forward strand). Ensembl gene ENSG00000210174.
Gene-disease validity (ClinGen):
ClinGen rates the evidence that MT-TR causes each of these diseases.
mitochondrial disease (mitochondrial): Moderate.
Diseases named in the same sentence as MT-TR in open-access papers:
MT-TR is named in the same sentence as 7 diseases in open-access papers, as found by Europe PMC text mining. Sharing a sentence is not in itself a finding about the gene and the disease. The quoted sentences say what the papers report.
hemophilia A (1 paper, 2025). The most common form of hemophilia characterized by spontaneous or prolonged hemorrhages due to factor VIII deficiency. "A similar enTTR-mTTR promoter, but with the mTTR enhancer in the antisense orientation, was used in gene therapies for the treatment of hemophilia A (TAK-754/BAX 888) and hemophilia B (AskBio009/BAX 335)." (PMID 41511298, 2025). "The mTTR mut promoter with the mentioned mutation was subsequently used for factor VIII expression in AAV-mediated gene therapies SPK-8011 and NGGT003 for hemophilia A without an enhancer region due to AAV vector capacity limitations." (PMID 41511298, 2025).
synovitis (1 paper, 2017). Inflammation of a synovial membrane. "The main observation from the present study is that hTTR‐TG mice develop more severe cartilage damage and synovitis than WT and mTTR‐KO mice in the surgically induced OA model and aging model." (PMID 28941045, 2017).
MT-TR also shares sentences with these, for which no sentence is quoted: amyloidosis (2 papers); aortic stenosis (1); cardiac amyloidosis (1); carpal tunnel syndrome (1); light chain amyloidosis (1).